IL17A (interleukin 17A)
Diseases named in the same sentence as IL17A in open-access papers (continued):
Sharing a sentence is not in itself a finding about the gene and the disease.
autism (continued). "Meanwhile, monocytes stimulated with LTA, neutrophils stimulated with IL-17A, and NK cells stimulated with IL-12/IL-18 or K562 cells showed differential responses in each of these cell types in autism, as compared with the controls." (PMID 36268027, 2022). "IL-17A promotes sociability in the mouse model of neurodevelopmental disorder, and increased production of IL-17A in pregnant mothers can promote autism-like phenotypes in offspring." (PMID 33671196, 2021). "Prominent examples include the observation that the maternal interleukin-17a pathway in mice promotes autism-like phenotypes in offspring." (PMID 34349112, 2021). "Different transcription factors related to the immune system have been recently associated to ASD, in fact, it was shown that the maternal Th17 cells, through the interleukin-17a pathway, promote autism-like phenotypes in offspring in mice." (PMID 32106489, 2020). "In this study, we found that serum IL-17A levels were increased in some children with autism, and were significantly correlated with the severity of autism." (PMID 22748016, 2012). "Further research is warranted to determine the possible link between increased serum levels of IL-17A and the presence of brain-specific auto-antibodies in some children with autism." (PMID 22748016, 2012). "Serum IL-17A levels were raised in the group with autism, and the levels correlated significantly with the severity of autism." (PMID 22748016, 2012). "This is the first study to measure levels of IL-17A in relation to the severity of autism, to our knowledge." (PMID 22748016, 2012). "The aim of this study was to measure serum levels of IL-17A in relation to the degree of the severity of autism." (PMID 22748016, 2012). "In this study, we aimed to measure serum IL-17A levels in a group of children with autism, and to examine the relationship between serum levels of IL-17A and the degree of the severity of autism." (PMID 22748016, 2012). "Children with autism had significantly higher serum IL-17A levels than healthy controls (P <0.001), with increased serum levels of IL-17A found in 48.9% of the autism group." (PMID 22748016, 2012). "In our series, children with autism had significantly higher serum IL-17A levels than healthy controls (P <0.001)." (PMID 22748016, 2012). "Serum IL-17A levels were measured by ELISA in 45 children with autism and 40 matched healthy controls." (PMID 22748016, 2012). "In addition, studies have shown a correlation between IL-17a and polarization of microglia, and glial cells also play an important role in the pathophysiology of autism." (PMID 38993386, 2024). "On the other hand, several other studies did not reveal any association between serum IL-17 A levels and autism." (PMID 38183030, 2024). "Whether the change of IL-17a is a key factor for taVNS to play a role in improving the social function of autism model mice is worth further exploration." (PMID 38993386, 2024). "Studies have shown that IL-17a can improve behavioral deficits in experimental models of autism, and immune cells and derived factors in the brain play important roles in improving autism symptoms." (PMID 38993386, 2024). "It has also been reported that autism-like symptoms in the offspring of immune-activated maternal mice may be due to IL-17A signalling." (PMID 37108638, 2023). "Elevated levels of IL-17A have been detected in children with autism." (PMID 33671196, 2021). "Specifically, IL17a mediates alterations in cortical neuron numbers and organization as well as autism-related behavior in offspring, which could be prevented via attenuation of IL17a in vivo." (PMID 34158620, 2021). "Association studies might consider any correlations between outcomes of MAR autism and maternal infection during pregnancy or interleukin 17A (IL17A) in gestational plasma samples." (PMID 32784803, 2020).
autism (continued). "Additionally, IL-17A was found to be significantly higher in the serum of autistic children than healthy controls, and higher levels correlated with severity of autism." (PMID 30498564, 2018). "Patients with severe autism had significantly higher serum IL-17A levels than those with mild to moderate autism (P = 0.01), and raised serum IL-17A levels were significantly more common in children with severe autism (67.9%) than in those with mild to moderate autism (17.6%), P = 0.001." (PMID 22748016, 2012). "Children with autism had significantly higher serum IL-17A levels than healthy controls (P <0.001." (PMID 22748016, 2012). "Raised serum IL-17A levels were found in 48.9% (22/45) of the patients with autism." (PMID 22748016, 2012). "The role of anti- IL-17A therapy in autism should also be studied." (PMID 22748016, 2012). "Increased serum IL-17A levels were found in 48.9% (22/45) of the patients with autism." (PMID 22748016, 2012). "Further extensive studies will be needed that include more advanced techniques for multiplex cytokine detection with long follow-up periods to evaluate better serum IL-17 A and IL-22 levels and functions in pediatric patients with autism and to confirm whether IL-22 correlates to ASD severity." (PMID 38183030, 2024). "Furthermore, neutralizing IL-17a improved social function in autism model mice." (PMID 38993386, 2024). "Another possible reason is that, unlike in the polyinosinic-polycytidylic acid-induced autism model, IL-17a may be not sufficient to cause aberrant lamination and social deficits in this LPS-induced MIA model." (PMID 30103815, 2018). "Thus, increased serum osteopontin levels in autism may be another contributing factor to the elevation of serum IL-17A levels in children with autism." (PMID 22748016, 2012). "We investigated the influence of 5-AIQ-treatment in BTBR T+ Itpr3tf/J (BTBR) mice as an autism model and used flow cytometry to assess the effect of 5-AIQ on FOXP3, Helios, GATA3, IL-9, IL-10 and IL-17A production by CXCR6+ and CD4+ T cells in the spleen." (PMID 33671196, 2021). "IL-17A was reported to have a possible role in some autoimmune neuroinflammatory diseases, thus the increased serum levels of IL-17A found in our study may be a possible contributing factor to the increased frequency of the brain-specific auto-antibodies in some children with autism." (PMID 22748016, 2012). "However, it is not clear whether the increase in serum IL-17A levels is a mere consequence of autism or has a pathogenic role in the disease." (PMID 22748016, 2012). "Increased levels of pro-inflammatory cytokines, such as interleukin-17 A (IL-17 A), tumor necrosis factor-alpha (TNF-alpha), and interleukin-1 beta (IL-1β), have been observed in the blood and cerebrospinal fluid of individuals with autism." (PMID 38475688, 2024). "Our results showed that maternal diabetes-mediated autism-like offspring had significant GI symptoms, together with suppressed RORA expression in PBMC and increased secretion of proinflammatory cytokines, including IL1β, IL6, MCP1 and IL17A." (PMID 35164690, 2022). "IL-17A, the main TH17 cytokine has been found elevated in the serum of some children with autism." (PMID 35495047, 2022). "Elevated serum levels of IL-6 and IL-17A, increased serum IL-6 level, and increased expression of the inflammatory molecules IL-1β, IL-6, IL-17, and TNF have been observed in children with autism." (PMID 31293459, 2019).
dry eye (45 papers, 2011 to 2025). "In this study, we selected several inflammatory cytokines associated with dry eye, including IL-17A, IL-10, IL-12p70, INF-γ, IL-6, and TNF-α." (PMID 34659636, 2021). "Desiccating stress in the murine dry eye model, similar to human dry eye, also causes ocular surface inflammation characterized by increasing IL-6 and IL-17A expression." (PMID 23956763, 2013). "Studies have shown increased expression of IL-17A in both animal models of dry eye and the ocular surface of patients with DED." (PMID 39903182, 2025). "The combined activation of JAK-STAT, NF-κB, and IL-17A pathways suggests a mechanism for sustained immune activation and tissue injury, contributing to the progression of dry eye pathology." (PMID 40890823, 2025). "We previously reported that γδT cells are the main cells that secrete IL-17A in the conjunctiva, which exacerbates dry eye symptoms." (PMID 39903182, 2025). "We analyzed retention of an antibody to IL-17A because intraperitoneal injection of antibodies to IL-17A has been shown to reduce dry eye signs in mouse models." (PMID 37130912, 2023). "Application of a WGA-conjugated antibody to IL-17A just once daily is sufficient to treat dry eye in a mouse model whereas the unconjugated antibody is ineffective." (PMID 37130912, 2023). "A role for IL-17A in dry eye has been suggested by its increased levels at the ocular surface in animal models and in humans." (PMID 37130912, 2023). "It should be considered that the regulation of osmolarity has a great impact on the dry eye inflammatory cycle, leading to significant reduction of inflammatory markers in tears (especially IL-17A and IL-6), as demonstrated in previous reports." (PMID 35361273, 2022). "Both inflammatory expression products (IL-1α, and IL-17A with p = 0.030 and p = 0.004) were upregulated in untreated dry eye, compared to control." (PMID 33057006, 2020). "We and others have shown that IL-17A disrupts apical corneal barrier apical function in experimental dry eye, by stimulating matrix metalloproteinases that have been implicated in breakdown of epithelial tight junctions." (PMID 27623073, 2016). "Likewise, CD25-deficient mice with Sjögren-like keratoconjunctivitis sicca displayed increased CD4+ and CD8+ T cells in conjunctiva, along with elevated IL-17A and CCL20 mRNA expression in corneal and conjunctival tissues compared with wild-type mice." (PMID 41300932, 2025). "Furthermore, in vivo neutralization of IL-17A ameliorates dry eye and adaptive transfer of CD4+ IL-17A producing cells induces the disease in naïve mice in several models." (PMID 37130912, 2023). "Importantly, antibodies to IL-17A, IL-23, and IL-1β conjugated to the agglutinin reduces manifestations of dry eye, even when applied just once daily." (PMID 37130912, 2023). "Interferon-γ and IL-17A induced dry eye surface injury and the density of goblet cells in mice." (PMID 34659636, 2021). "The expression of IL-17A was also significantly increased in untreated dry eye." (PMID 33057006, 2020). "One study reported CD8+T cells may attenuate dry eye by decreasing IL-17A producing cells in the B6 mouse model." (PMID 29068389, 2017). "Our published study showed that 24 month-old C57BL/6 mice spontaneously develop a SS-like keratoconjunctivitis sicca, with increased IL-17A and IFN-γ transcript levels in conjunctiva, which was accompanied by loss of conjunctival goblet cells and increased corneal barrier disruption." (PMID 27623073, 2016). "Therapies targeting both IFN-γ and IL-17A cytokines may be needed to fully address the spectrum of dry eye manifestations and to improve the quality of visual function and life of an aging population." (PMID 27623073, 2016). "Increased levels of IL-17A have been reported in both tears and conjunctiva of dry eye patients." (PMID 27623073, 2016).
dry eye (continued). "We also observed that the pattern of T cell related cytokines in human dry eye patients and mice subjected to the adverse environment are similar, and we have found an increase in expression of matrix metalloproteinases, IL-17A, IFN-γ and TGF-β1, among many other markers." (PMID 22194977, 2011). "Our LPA analysis found that IL-6 and IL-8 were higher in subgroup 1 that had more severe dry eye signs, while IL-10, IL-17A, and IFN-γ were higher in subgroup 2 that had less severe dry eye signs." (PMID 38177232, 2024). "In another study, higher levels of IL-17A, TGF-β1, TGF-β2, IL-6, IL-23, and IL-1 mRNA transcripts were observed in the corneal epithelium and conjunctiva of dry eye mice." (PMID 25590134, 2015). "However, in the TCRδ–/– mice, the upregulation of IL-23 failed to increase the expression level of IL-17A and the severity of dry eye." (PMID 39903182, 2025). "IL-17A may be related to inflammation in dacryoadenitis and in the salivary glands, while MMP-9 may be involved in the early phase of dry-eye syndrome and tissue fibrosis." (PMID 34630072, 2021). "Here we report that suppression of IL-17A by IFN-γ occurs naturally even in young mice, but a significant clinical phenotype (corneal barrier disruption) is only found with advanced aging, demonstrating that a certain accumulation of still unknown events is necessary for a full dry eye phenotype." (PMID 27623073, 2016).
hidradenitis suppurativa (43 papers, 2019 to 2026). A chronic suppurative and cicatricial disease of the apocrine glands occurring chiefly in the axillae in women and in the groin and anal regions in men. "For patient 8, who experienced hidradenitis suppurativa (HS) while on treatment with ixekizumab, switching to secukinumab was a reasonable choice, as secukinumab, unlike ixekizumab has the approved therapeutic indication for this condition considering the role of IL-17A in the pathogenesis of HS." (PMID 39728081, 2024). "Secukinumab, a selective IL-17A inhibitor, has shown significant efficacy in phase III trials, with clinically meaningful improvements in Hidradenitis Suppurativa Clinical Response (HiSCR), pain, and quality of life, sustained over long-term follow-up." (PMID 42195203, 2026). "Both, hidradenitis suppurativa and VKHD are driven by IL-17A and IL-17F." (PMID 41142785, 2025).
mastitis (42 papers, 2013 to 2026). Inflammation of breast tissue during lactation or postpartum due to an obstructed duct or infection. "Some reports have shown that IL-17A can be used as an important indicator for assessing the bacterial infections of mammary glands, and there is IL-17A generated in mastitis caused by streptococcus or S. aureus infections." (PMID 38891619, 2024). "IL-17A is produced or its encoding gene overexpressed in the bovine MG during mastitis caused by Escherichia coli, Streptococcus uberis or Staphyloccus aureus." (PMID 27100324, 2016). "IL-17A and IL-17 F have been implicated in modulation of mammary gland immune responses to mastitis causing bacteria." (PMID 24996426, 2014). "In conclusion, both IL-17A and IL-17F gene polymorphisms (g.24392436C > T and g.24345410A > G) may provide valuable information for predicting the prognosis of bovine mastitis." (PMID 28101335, 2017). "In the present study, a total of 12 SNPs were identified in IL-17F and IL-17A genes in Holstein and Inner-Mongolia Sanhe cattle, of which 2 SNPs were arbitrarily chosen for genotyping and further screening to evaluate their potential association with mastitis." (PMID 28101335, 2017). "Additionally, the findings provide the first proof that the cytokine IL-4 of bovine mastitis is highly correlated with the IL-17A promoter polymorphism, whose function is still unknown." (PMID 36134995, 2022). "Studies have shown that in naturally occurring subclinical mastitis in cows, the intramammary inflammatory response is driven by IL–1α, IL–4, IL–12, IL–17A, and IFN–γ." (PMID 40005889, 2025). "Subclinical and clinical mastitis data demonstrate inflammatory responses to intramammary infection driven by IL-1α, IL-4, and IL-17A." (PMID 39195804, 2024). "In general mastitis cases, immunoreactivity was more pronounced for IL-4, IL-6, IL-12, IL-13, IL-17A, TNF-α, and IFN-γ." (PMID 39195804, 2024). "This provides a new idea and perspective for us to use to study IL-17A in bacterial cow mastitis in the future." (PMID 38891619, 2024). "The blockage of IL-17 with the anti-IL-17A antibody has been shown to protect dairy cows from LPS-induced mastitis by suppressing the pro-inflammatory cytokine levels, myeloperoxidase activity, and neutrophil infiltration and NF-κB signaling pathway." (PMID 36911690, 2023). "Data about subclinical and clinical mastitis demonstrate inflammatory responses to intramammary infection driven by IL-1α, IL-4, and IL-17A." (PMID 35335696, 2022). "The role of IL-17F and IL-17A progression in animals indicates that they can be candidate genes for mastitis tolerance in cattle." (PMID 36134995, 2022). "For IL-17A immunoreactivity in milk mostly weakly (+) stained cells of subclinical mastitis cows, the mean positive cell counts (%) increased from 84.2 cells on day 4 to 84.8 on day 5 to 91.6 on day 6, with most cells being positive for IL-17A." (PMID 35335696, 2022). "In subclinical mastitis-affected cows, the highest means of immunoreactive cell counts were observed for IL-4 and IL-17A." (PMID 35335696, 2022). "In mastitis cases, immunoreactivity was more pronounced for IL-4, IL-6, IL-12, IL-13, IL-17A, TNF-α, and IFN-γ." (PMID 35335696, 2022). "It has been reported that IL-17A and IL-17F play a critical role in regulating host–pathogen interactions during the development of mastitis." (PMID 33202860, 2020). "Experimental infection with a mastitis S. aureus strain of goat origin revealed an early influx of γδT cells producing IL-17A into the MG." (PMID 33059767, 2020). "IL-17A production was documented during S. uberis mastitis, and slightly increased expression was also noticed in the somatic cells of cows infected with S. aureus." (PMID 33202860, 2020). "By contrast, IL-17A rose sharply in the milk of the goats that developed gangrenous mastitis, reaching a maximum at their last sampling." (PMID 30045763, 2018).